GSK3B (glycogen synthase kinase 3 beta)
Diseases named in the same sentence as GSK3B in open-access papers (continued):
Sharing a sentence is not in itself a finding about the gene and the disease.
prostate carcinoma (continued). "In prostate cancer, it promotes cell expansion by targeting SFRP1 and GSK3β." (PMID 33363159, 2020). "Additionally, litchi seed extracts can halt prostate cancer progression via induction of apoptosis and attenuation of EMT through AKT/GSK-3β signaling." (PMID 31772677, 2019). "In prostate cancer, HN1 interacts with GSK3β/β-catenin destruction complex." (PMID 28490334, 2017). "This indicates that bupivacaine induced prostate cancer cell death is unlikely to involve GSK3β activity." (PMID 27195613, 2016). "Interestingly, the administration of sorafenib increased the expression levels of the androgen receptor, p-GSK3β and p-ERK1/2 in castration-resistant prostate cancers." (PMID 25953027, 2015). "Targeting of critical intra- and extracellular focal adhesion components in prostate cancer cells, specifically talin, ILK, integrin-α6 and fibronectin by lead agent DZ-50, lifts anoikis resistance by inhibiting downstream survival signaling by AKT and GSK3β." (PMID 24497940, 2014). "Based on our observation that the cellular morphology of prostate cancer cells was disturbed following GSK-3β inhibition and a previous study pointing out a link between GSK-3β and F-actin, we performed a DAPI/Phalloidin double staining to monitor F-actin polymerization." (PMID 25344861, 2014). "GSK3β appears to be an attractive candidate kinase for the regulation of USF2 since both proteins seem to be involved in the development of different types of cancer, especially prostate cancer." (PMID 25238393, 2014). "Second, our study highlights a distinctive difference in the effect of NDRG1 overexpression in PC cells relative to our previous findings using colon and prostate cancer cells where no significant (p > 0.05) change in total GSK-3β levels or its activation was observed." (PMID 38815861, 2024). "Indeed, Src was reported to induce Tyr216 phosphorylation of GSK-3β in PC3, prostate cancer cells." (PMID 32046944, 2020). "As several studies indicated that GSK-3β is one of the targets of luteolin in several types of cancers, we next investigated whether FZD6-mediated inhibitory effect of luteolin is GSK-3β-independent in prostate cancer." (PMID 29867083, 2018). "To investigate whether the decrease in HIF-1α expression by CA in hypoxic prostate cancer cells involves in the SPHK-1 pathway, AKT, and GSK-3β and to delineate the downstream signaling mechanism of SPHK-1, we performed western blot analysis and SPHK-1 activity assay." (PMID 28165392, 2017). "Thus, our results demonstrated that GSK3α, and not GSK3β is necessary for the prostate cancer cell proliferation, survival and colony formation in vitro and tumor xenograft growth in vivo." (PMID 25714023, 2015). "We now show that blockage of GSK-3β activity leads to a massive reduction in the size of this highly tumorigenic cellular subpopulation of ALDHHIGH prostate cancer cells with a concomitant reduction in clonogenic and migratory potential of human prostate cancer cell lines." (PMID 25344861, 2014). "Similarly, TNF sensitization by lithium in multiple sarcoma cell lines was found to be independent of both GSK-3β and NF-κB while GSK-3β inhibition in prostate cancer and HEK cells actually increased NF-κB activity despite promoting TNF-induced apoptosis." (PMID 22675363, 2012). "Given that LD accumulation in our experimental setting occurred through the GSK3β-PPARα signaling axis downstream of PIM1, we hypothesized that blocking PPARα could counteract the known positive effect of PIM1 induction on cell proliferation in prostate cancer." (PMID 38097734, 2024). "We report that silencing of GSK3α, but not GSK3β expression inhibited proliferation, survival and colony formation by the PC3, DU145 and LNCaP prostate cancer cells, and the growth of PC3 tumor xenografts in athymic nude mice." (PMID 25714023, 2015).
prostate carcinoma (continued). "Concomitant treatment with TQ and the PI3K inhibitor LY294002 leads to an additive reduction of p-GSK-3β, assuming that, in colon cells, TQ does not utilize the PI3K/AKT pathway, as shown for prostate cancer." (PMID 23668310, 2013). "In order to determine the isoform specific role of GSK3 in the regulation of prostate cancer cell growth and proliferation, we generated PC3, DU145 and LNCaP stable cell lines expressing ShRNAs for control (non-target), GSK3α and GSK3β (ShControl, ShGSK3α and ShGSK3β, respectively)." (PMID 25714023, 2015). "In addition to the experiments in HeLa cells, we were able to show that GSK3β-dependent phosphorylation of USF2 also occurs in HepG2 cells and in the human prostate cancer cell lines LNCaP and PC-3 (data not shown)." (PMID 25238393, 2014).
depression (144 papers, 2010 to 2026). "Collectively, this study found that CUMS-induced depression is associated with a significant upregulation of hippocampal Wnt7a, β-catenin, and GSK-3β, along with increased GSK-3β phosphorylation." (PMID 41732723, 2026). "Studies show that whereas lower phosphorylated GSK3β correlates with the severity of depression, greater CREB activity and decreased BDNF levels are linked to AD, particularly in the moderate to severe stages of dementia." (PMID 40149774, 2025). "The pathophysiology of neuropsychiatric disorders, including depression, is linked to a disrupted serine/threonine kinase glycogen synthase kinase 3β (Akt/GSK3β signaling pathway)." (PMID 40431406, 2025). "According to research with mice fed a high-fat diet, the consequential obesity induced desensitizing of serotonin-dependent Akt/GSK3β signaling and caused depression." (PMID 40431406, 2025). "For example, the SCN2A and GSK3B genes are associated with major depressive disorder and schizophrenia in the Han Chinese population." (PMID 39452151, 2024). "In a social defeat model of depression, reduced levels of specific forms of GSK-3β within the nucleus accumbens (NAc) were linked to increased susceptibility to chronic stress, in connection with the canonical Wnt/β-catenin signaling pathway." (PMID 39484582, 2024). "Single nucleotide polymorphisms in the GSK3β gene affect the induction of depression or its age of onset." (PMID 37807001, 2023). "Intracellular signaling pathways in the brain involving ERK1/2, GSK3β and mammalian/mechanistic target of rapamycin (mTOR) have been implicated in depression in humans and in antidepressant response in animal models." (PMID 37775532, 2023). "Our data support the role of this pathway in the WKY strain and perhaps explain a potential mechanism of drug resistance in depression associated with Gsk-3β hyperactivity." (PMID 36983013, 2023). "CUMS-induced depression-like behavior was associated with protein kinase B (AKT)/GSK-3β signaling, while swimming significantly increased CREB/BDNF and AKT/GSK-3β signaling in the hippocampus of CUMS mice, and the expression of BDNF was upregulated." (PMID 37239191, 2023). "Literature data indicate that risk factors for depression initiate an infection-like inflammation in the brain that involves activation of microglial Toll-like receptors and glycogen synthase kinase-3β (GSK3β)." (PMID 36979785, 2023). "Risk factors for depression initiate an infection-like inflammation in the brain that involves activation microglial Toll-like receptors and glycogen synthase kinase-3β (GSK3β)." (PMID 36979785, 2023). "Dysregulated Akt/GSK-3β/β-catenin pathway is directly associated with the most prevalent neuropsychiatric disorders such as schizophrenia, anxiety, depression, and bipolar disorder." (PMID 35943710, 2022). "CRMP2, a phosphorylation target of GSK3β, has been implicated in various models of depression induced by stress." (PMID 36776771, 2022). "Collapsin response mediator protein 2 (CRMP2) is a phosphorylation target of GSK3β that has been implicated in schizophrenia, AD and depression." (PMID 36776771, 2022). "Recently, PI3K/Akt/GSK-3β/mTOR signaling pathway has been associated to neurobiology of depression and seems to be modulated by some pharmacological antidepressant strategies." (PMID 34790666, 2021). "Comparison of genotypes and alleles of GSK-3β rs6438552, rs334558, and rs2199503 gene polymorphisms between the depression and control groups." (PMID 33658947, 2020). "Our results suggest that GSK-3β rs6438552, rs334558, and rs2199503 polymorphisms are a susceptibility site for depression." (PMID 33658947, 2020). "GSK-3β gene single nucleotide polymorphisms [SNPs] (rs6438552, rs2199503, and rs334558) are associated with symptoms of depression in the Chinese population." (PMID 33658947, 2020).
depression (continued). "Abnormally active GSK3β has been demonstrated to increase the susceptibility to depression-like behavior, memory impairment, and impaired hippocampal neural precursor proliferation." (PMID 31338065, 2019). "Rats with subclinical hypothyroidism-associated depression exhibited increased levels of GSK-3β and phosphorylated β-catenin, while c-myc and cyclin D1 were decreased." (PMID 30200269, 2018). "Acute stress, PKC inhibition and certain GSK3β inhibitors increase neurotransmitter release, causing overactivation of their altered NMDARs and the subsequent development of depression-like behaviors." (PMID 28240305, 2017). "Consistent with previous findings on depressed rats and patients, our results further confirmed that insufficient GSK-3β inhibition is a risk factor of depression." (PMID 26798520, 2015). "There were 25 SNPs in GSK3B associated with depression with nominal P<0.05, falling into several linkage groups, and the gene-wise set test was nominally significant in the DSPS data set." (PMID 23521777, 2013). "Genetic variations in GSK-3β have also been linked with the risk to depressive disorders, and most notably to bipolar disorder." (PMID 23521808, 2013). "Recently, it has been shown that blockade of Dvl function and over-expression of GSK3β in the nucleus accumbens render mice more susceptible to social defeat stress and promote depression-like behaviour." (PMID 23449817, 2012). "In summary, we propose that PTEN may alleviate neurological damage associated with depression through the AKT/GSK3β/β-catenin pathway." (PMID 40043208, 2025). "BDNF, a neurotrophin, and GSK3β, a versatile kinase, are key regulators implicated in depression." (PMID 40149774, 2025). "First, GLP1R agonists have been associated with the over-activation of GSK3β (glycogen synthase kinase-3β) in a depression model of chronic corticosterone (CORT) administration in mice, suggesting a potential link between GLP1R signaling and GSK3β-related pathways." (PMID 40770700, 2025). "Moreover, DVL3 suppresses the expression of major proteins associated with AD and depression by inhibiting the activity of GSK3β." (PMID 37501340, 2024). "GSK3β, initially described as a negative regulator of glycogen synthesis, is a molecular hub linking numerous signaling pathways in a cell, possibly linked to symptoms of depression." (PMID 39565757, 2024). "Previous studies have shown that GSK3β is associated with AD and depression." (PMID 37501340, 2024). "We hypothesized the existence of a mental GSK-3 disease, which comprises a specific group of patients associated with the GSK-3β variant, whose diagnoses longitudinally transition from depression to bipolar disorder and finally to dementia." (PMID 39228919, 2024). "In addition, we previously reviewed that rs334558 of the GSK-3β gene was associated with depression, bipolar disorder, and dementia." (PMID 39228919, 2024). "Phospho‐glycogen synthase kinase‐3 beta (GSK3β) is known to be associated with AD and depression." (PMID 37501340, 2024). "Dysregulation of Wnt/GSK-3β signaling is associated with a lifetime of major depression." (PMID 38743109, 2024). "Similarly, increased GSK3β activity in the platelets was suggested to associate with the pathophysiology of both depressive disorder and neurodegenerative diseases." (PMID 36991130, 2023). "As a downstream target of Sema3A, GSK3β is thought to be associated with major depression." (PMID 36776771, 2022). "Notably, regulation of GSK3β has been implicated in antidepressant mechanisms of action and in the pathogenesis of depression." (PMID 36055984, 2022). "Importantly, EGCG alleviated gestational stress-induced postpartum anxiety and depression symptoms, which was associated with the downregulation of Sema3A and increase of phosphorylated GSK3β in the hippocampus." (PMID 36776771, 2022).
depression (continued). "As the Akt-GSK3β signaling pathway is strongly linked to long term potentiation, depression and neuroinflammation, these experiments may illustrate potential biochemical underpinnings of cognitive changes that occur with alterations in light exposure." (PMID 33809219, 2021). "The protein kinase GSK3β has been implicated in mediating anxio-depressive disorders." (PMID 34121997, 2021). "After rapid anti-depression treatment with ketamine, the phosphorylation level of GSK-3β in plasma increases significantly, suggesting that GSK-3β may be involved in the mechanism underlying anti-depression." (PMID 33658947, 2020). "In conclusion, GSK-3β may be a susceptibility gene for depression and is involved in the pathophysiological and therapeutic processes of MDD." (PMID 33658947, 2020). "Furthermore, β-catenin stabilization or GSK3β inhibition was able to reverse schizophrenia- and depression-like behaviors as well as the associated cellular phenotype." (PMID 29449801, 2018). "Moreover, GSK-3β is now believed to play an important role in the pathophysiology of depression and is implicated to be a drug target for the treatment of depression." (PMID 29364170, 2018). "Mammalian target of rapamycin (mTOR), Ca2+/calmodulin-dependent protein kinase 2γ (Camk2γ) and glycogen synthase kinase-3β (GSK-3β) are three fundamental biomarkers implicated in the underlying mechanisms of depression, schizophrenia, mania and certain neuropsychiatric diseases." (PMID 24396420, 2014). "This evidence supports previous reports that GSK3B has a role in affective responses to lithium and may be associated with bipolar disorder and unipolar depression." (PMID 23521777, 2013). "The expression levels of GSK3β are associated with depression- and anxiety-like behaviours, as shown by an increased exploratory activity, reduced amphetamine-induced hyperactivity, and reduced immobility in the forced swim test in mice lacking one copy of the GSK3β gene." (PMID 23449817, 2012). "Furthermore, serine-threonine protein kinase (Akt), an upstream regulator of GSK3β, could facilitate GSK3β phosphorylation to inhibit GSK3β activity and thus has been implicated in modulating depression and other neuropsychopathies." (PMID 38038373, 2024). "The rs6438552 allele is closely related to the superior temporal gyrus of patients with depression and the decline of gray brain volume in the right hippocampus, and it was suggested that GSK-3β could be a susceptibility gene to MDD in the Chinese Han population." (PMID 33658947, 2020). "The protein kinase GSK3β has been extensively studied in the context of depression, with recent reports suggesting it plays an essential role in the etiology and pharmacotherapy of this disorder." (PMID 41226527, 2025). "Glycogen synthase kinase 3β (GSK-3β) represents another critical regulatory hub integrating multiple signaling pathways involved in depression pathogenesis." (PMID 41516220, 2025). "Loganin, another component of Cornus officinalis, alleviates gap junction dysfunction in astrocytes of the prefrontal cortex and hippocampus in depression models via the GSK-3β/β-catenin signaling pathway." (PMID 41403435, 2025). "We verified that overexpression of miR-182-5p not only significantly decreased expression levels of Akt/GSK3β/CREB signal pathway in the hippocampal area but also led to depression-like behaviors in CSDS mice." (PMID 38038373, 2024). "GSK3β is closely associated with the AD proteins PS2 and MAPT and with the depression‐related proteins NR3C1 and DKK‐1." (PMID 37501340, 2024). "Other research has demonstrated the downregulation of phosphorylated GSK3β in the nucleus accumbens in the mouse social defeat model of depression." (PMID 37501340, 2024). "Secondly, overexpression of miR-182-5p aggravated depression-like behaviors along with a progressive reduction in the number of DCX cells and the levels of Akt/GSK3β/CREB signal pathways as depression became worse." (PMID 38038373, 2024).